LAG3 (lymphocyte activating 3)
Diseases named in the same sentence as LAG3 in open-access papers (continued):
Sharing a sentence is not in itself a finding about the gene and the disease.
neurodegenerative disease (3 papers, 2020 to 2024). A disorder of the central nervous system characterized by gradual and progressive loss of neural tissue and neurologic function. "The major finding of this study is that Lag3 delays the progression of neurodegenerative disease in the hA53T α-syn transgenic mouse model." (PMID 33776654, 2021). "Repurposing LAG3‐blocking antibody combination therapy has been approved by the US FDA with PD‐1 inhibition and could be used for neurodegenerative diseases characterized by pathologic tau and α‐syn." (PMID 38327094, 2024).
cardiovascular disease (2 papers, 2022). "This LAG3-associated network analysis identifies novel targets for further study in HDL metabolism, cardiovascular diseases, and all-cause mortality." (PMID 35501457, 2022).
hematological tumor (1 paper, 2020). "It should be noted that unlike solid tumor cells, hematological tumor cells frequently express MHC-II, and thus, the LAG-3-MHC-II interaction still plays a key inhibitory role in CD4+ T cell-mediated control." (PMID 32787882, 2020).
LAG3 also shares sentences with these, for which no sentence is quoted: colorectal adenocarcinoma (5 papers); lung squamous cell carcinoma (3); nasopharyngeal carcinoma (3); testicular germ cell tumor (3); thymoma (3); B-cell acute lymphoblastic leukemia (2); breast invasive carcinoma (2); colorectal tumor (2); gastroesophageal junction adenocarcinoma (2); germ cell tumor (2); hepatitis C (2); hyperlipidemia (2); IgA nephropathy (2); immune thrombocytopenia (2); liver disease (2); Merkel cell carcinoma (2); ocular melanoma (2); primary central nervous system lymphoma (2); thyroid disease (2); viral diseases (2); acral melanomas (1); adenoma (1); adenomyosis (1); Alzheimer disease (1); antineutrophil cytoplasmic antibody-associated vasculitis (1); aplastic anemia (1); aspergillosis (1); autoimmune myocarditis (1); bacterial infection (1); benign salivary gland tumors (1).
A further 81 diseases each share a sentence with LAG3 in 1 paper.